GAB1 (GRB2 associated binding protein 1)
Diseases named in the same sentence as GAB1 in open-access papers (continued):
Sharing a sentence is not in itself a finding about the gene and the disease.
cancer (continued). "As the Grb2 binding site at Tyr177 in BCR is uniformly conserved among other BCR-fusion proteins, such as BCR-JAK2, BCR-PDGFRA, BCR-RET and BCR-NTRK2, our results suggest that Shp2 and Gab1 play an equally important role in cancers driven by these oncogenes as well." (PMID 35574218, 2022). "The GAB1 is a good candidate gene to test its functions in PCs and other adult cancers." (PMID 26073932, 2015). "Therefore, this study validates the effectiveness of our in silico platform for drug discovery, and demonstrates that targeting the PH domain of GAB1 provides a promising and novel therapeutic strategy for cancer treatment." (PMID 25569504, 2015). "Moreover, GAB1, which plays a significant role in cancer cell signaling pathways, had elevated levels in STS samples and could lead to reduced OS." (PMID 37237151, 2023). "GAB1, which is widely distributed in various body tissues, is capable of promoting cell proliferation, and its expression may enhance the carcinogenesis and cancer progression." (PMID 35498426, 2022). "Therefore, it is likely that dysregulated Gab1 significantly impacts on cell fate decisions and may contribute to cancer progression." (PMID 31651330, 2019). "The MBD Try1349 and 1356 provide a docking platform to recruit the Src homology-2 domain, phosphotyrosine-binding domain, and other critical MBD adapter proteins GAB1, GRB2, phospholipase C, and SRC required for activating cancer motility." (PMID 41470892, 2025). "Therefore, GAB1 could be considered a potential therapeutic target for cancer treatment." (PMID 37627207, 2023). "Although several studies determined the direct or indirect network between PIK3CA, KDR, GAB1, VEGFA, PLCG, and CRKL and hsa-miR-429 in various cancers, the functional regulation of these genes in Bag-1 deficiency conditions is still needed to elucidate." (PMID 37533517, 2022). "Using the DepMap database, we found among approximately 1,300 cancer cell lines, HNSCC cell lines were the most sensitive to GAB1 genetic editing." (PMID 36506869, 2022). "Analyses of gene dependencies found GAB1 and EGFR were most closely related, highlighting the importance of GAB1 for EGFR-driven cancers, like HNSCC." (PMID 36506869, 2022). "In the present study, TGFβ reduced HGF production in PSCs and reduced cancer cell mitogenesis and migration induced by the high HGF-producing PSCs concomitant with a reduction in phosphorylation of Gab1 and ERK in the cancer cells." (PMID 29069737, 2017). "Media from high-HGF-producing PSCs stimulated phosphorylation of Met, Gab1, and ERK in the cancer cells and induced increases in DNA synthesis and migration which were blocked by the Met inhibitor SU11274, indicating a role of HGF as a mediator." (PMID 29069737, 2017). "According to a large number of literature reports, the growth, invasion and metastasis of malignant tumors are closely related with VEGFR-2 and MMP-9, and the Gab1-mediated VEGFR-2 signaling pathway can promote cell growth and invasion." (PMID 24312291, 2013). "To determine whether pY sites of GAB1 and GAB2 exhibit the same pattern of response in other cellular contexts, we also treated other EGFR-driven cancer cell lines with SHP099." (PMID 33755016, 2021). "MiR-5582-5p by targeting GAB1, SHC1, and CDK2 could induce apoptosis and cell cycle arrest at G1 phase in cancer cells." (PMID 33330110, 2020). "Different important target genes have been validated in different cancers, such as the transcriptional regulator PHF10, the pro-metastatic gene radixin, the pro-angiogenic gene angiogenin (ANG), the oncoprotein GAB1 and the pro-metastatic gene c-Met." (PMID 27057640, 2016). "Indeed, multiple upstream regulators of Ras activation such as SOS1, SOS2, PTPN11, and GAB1 exhibit significant negative correlations with NF1 in the Cancer Dependency Map, supporting the importance of these genes as functionally opposing NF1 function." (PMID 40587782, 2025).
cancer (continued). "Therefore, the Grb2-SH2 domain and Gab1-MBD motif might function as epitope peptides to block the interaction of endogenous Grb2 or Gab1 with c-MET, thereby limiting the proliferation of cancer cells." (PMID 36233320, 2022).
infection (5 papers, 2015 to 2025). The state of being infected such as from the introduction of a foreign agent such as serum, vaccine, antigenic substance or organism. "Infection of rat neonatal cardiomyocytes with Ad-Gab1-WT was successful as demonstrated by the increase of Gab1 protein expression compared to cells infected with Ad-β-Gal." (PMID 26090437, 2015). "Moreover, hepatoma cells upon HCV infection decreased Gab1 mRNA at later times of infection (D3 to D5) and p-Gab1 level was inversely related to the production of TGF-β." (PMID 38935609, 2024). "We first examined the efficiency of cell infection by Ad-Gab1-WT." (PMID 26090437, 2015). "By expressing a GAB1 shRNA from the miR-US5-2 region, the levels of GAB1 were reduced compared to those seen with the parental ΔmiR-US5-2 virus and were similar to those measured for the WT infection." (PMID 32759334, 2020). "At 30 min p.i., infection with either B/03 or MPC/04 led to phosphorylation of Akt and FAK but not Gab1." (PMID 26388843, 2015).
inflammation (2 papers, 2020 to 2023). Aberrant reaction of the microcirculation characterized by movement of fluid and leukocytes from the blood into extravascular tissues. "Recent reports demonstrate the essential role for Gab1 in maintaining lung surfactant homeostasis and regulating acute lung inflammation and chronic asthmatic inflammation, as well as controlling tissue repair processes including pulmonary and liver fibrosis." (PMID 36795486, 2023). "Besides the well-known function for Gab1, increasing evidence demonstrates that Gab1 participates in LPS-induced acute lung inflammation, house dust mite–induced asthmatic inflammation, and vascular inflammation, highlighting the unique role for Gab1 in inflammation-associated diseases." (PMID 36795486, 2023).
gastrointestinal tumors (1 paper, 2013). "Gab1 has been reported to be closely involved in the occurrence, invasion and metastasis of tumors, particularly gastrointestinal tumors." (PMID 24312291, 2013).
GAB1 also shares sentences with these, for which no sentence is quoted: head and neck squamous cell carcinoma (3 papers); cholangiocarcinoma (2); chondrosarcoma (2); ependymoma (2); Noonan syndrome (2); urothelial cell carcinoma (2); acute kidney injury (1); alcohol abuse (1); arteriosclerosis obliterans (1); bronchopulmonary dysplasia (1); cardiovascular diseases (1); childhood asthma (1); Cirrhosis (1); demyelinating disease (1); diabetes (1); ectodermal dysplasia (1); embryonal carcinoma (1); gastric atrophy (1); heart diseases (1); inflammatory bowel disease (1); intrahepatic cholangiocarcinoma (1); ischemia (1); lymph node metastasis (1); neuroblastoma (1); neuroendocrine neoplasm (1); oral squamous cell carcinoma (1); osteosarcoma (1); Polycystic Ovarian Syndrome (1); preeclampsia (1); pterygium (1).
A further 5 diseases each share a sentence with GAB1 in 1 paper.